INTS15 (integrator complex subunit 15)
Description:
Component of the integrator complex, a multiprotein complex that terminates RNA polymerase II (Pol II) transcription in the promoter-proximal region of genes. The integrator complex provides a quality checkpoint during transcription elongation by driving premature transcription termination of transcripts that are unfavorably configured for transcriptional elongation: the complex terminates transcription by (1) catalyzing dephosphorylation of the C-terminal domain (CTD) of Pol II subunit POLR2A/RPB1 and SUPT5H/SPT5, (2) degrading the exiting nascent RNA transcript via endonuclease activity and (3) promoting the release of Pol II from bound DNA. The integrator complex is also involved in terminating the synthesis of non-coding Pol II transcripts, such as enhancer RNAs (eRNAs), small nuclear RNAs (snRNAs), telomerase RNAs and long non-coding RNAs (lncRNAs). INTS15 is part of the integrator tail module that acts as a platform for the recruitment of transcription factors at promoters. Within the integrator complex, INTS15 is required to bridge different integrator modules.
Synonyms: C7orf26; MGC2718
Tractability: PROTAC: ubiquitination databases record sites on it.
Gene: Protein-coding gene on chromosome 7 (6,589,978 to 6,608,726, forward strand). Ensembl gene ENSG00000146576.
Subcellular location: Nucleus; Chromosome
Subcellular location (Human Protein Atlas): Nucleoplasm; Cytosol; Mitotic spindle
Gene Ontology:
Biological process: regulation of transcription elongation by RNA polymerase II; RNA polymerase II transcription initiation surveillance; snRNA processing
Cellular component: chromosome; INTAC complex; integrator complex; nucleus
Genetic constraint (gnomAD): Loss-of-function variants: 7 observed, 33.99 expected, observed/expected ratio (o/e) 0.21, 90% interval 0.12 to 0.39. The synonymous counts are far from expectation, so gnomAD's model fits this gene poorly and the ratio says little. Missense variants: 711 observed, 569.59 expected, observed/expected ratio (o/e) 1.25, 90% interval 1.17 to 1.33. Synonymous variants: 321 observed, 257.58 expected, observed/expected ratio (o/e) 1.25, 90% interval 1.14 to 1.37.
Homologues: Orthologues: chimpanzee INTS15 (100% identical), macaque INTS15 (99% identical), guinea pig INTS15 (97% identical), dog INTS15 (96% identical), pig INTS15 (96% identical), mouse Ints15 (95% identical), rat Ints15 (95% identical), rabbit INTS15 (94% identical), tropical clawed frog ints15 (74% identical), zebrafish ints15 (61% identical), Drosophila melanogaster CG5274 (26% identical), Caenorhabditis elegans Y56A3A.31 (18% identical).
Diseases named in the same sentence as INTS15 in open-access papers:
INTS15 is named in the same sentence as 2 diseases in open-access papers, as found by Europe PMC text mining. Sharing a sentence is not in itself a finding about the gene and the disease.
INTS15 shares sentences with these, for which no sentence is quoted: cancer (2 papers); asthma (1).